GOLGA6L9 (golgin A6 family like 9)
Synonyms: GOLGA6L20
Tractability: PROTAC: ubiquitination databases record sites on it.
Gene: Protein-coding gene on chromosome 15 (82,429,816 to 82,439,153, forward strand). Ensembl gene ENSG00000197978.
Gene Ontology:
Molecular function: protein binding
Genetic constraint (gnomAD): Loss-of-function variants: 18 observed, 24.63 expected, observed/expected ratio (o/e) 0.73, 90% interval 0.5 to 1.08. The upper end of that interval is the gene's LOEUF score, 1.08, which puts it in group 4 of 6, group 1 being the genes least tolerant of losing a copy. Missense variants: 229 observed, 245.81 expected, observed/expected ratio (o/e) 0.93, 90% interval 0.84 to 1.04. Synonymous variants: 89 observed, 88.78 expected, observed/expected ratio (o/e) 1, 90% interval 0.84 to 1.2.
Homologues: Paralogues in human: GOLGA6L10 (99% identical), GOLGA6L4 (98% identical), GOLGA6L2 (31% identical), GOLGA6L22 (30% identical), GOLGA6L24 (30% identical), GOLGA6L25 (30% identical), GOLGA6L6 (29% identical), GOLGA6L1 (28% identical), GOLGA6L26 (28% identical), GOLGA6L7 (28% identical).